BCAS4 (breast carcinoma amplified sequence 4)
Synonyms: FLJ20495; CNOL
Tractability: PROTAC: ubiquitination databases record sites on it; its protein half-life has been measured.
Gene: Protein-coding gene on chromosome 20 (50,794,894 to 50,877,178, forward strand). Ensembl gene ENSG00000124243.
Subcellular location: Cytoplasm
Subcellular location (Human Protein Atlas): Cytosol; Intermediate filaments
Gene Ontology:
Cellular component: BLOC-1 complex; cytoplasm
Genetic constraint (gnomAD): Loss-of-function variants: 9 observed, 14.53 expected, observed/expected ratio (o/e) 0.62, 90% interval 0.37 to 1.08. The upper end of that interval is the gene's LOEUF score, 1.08, which puts it in group 4 of 6, group 1 being the genes least tolerant of losing a copy. Missense variants: 225 observed, 231.38 expected, observed/expected ratio (o/e) 0.97, 90% interval 0.87 to 1.09. Synonymous variants: 101 observed, 97.2 expected, observed/expected ratio (o/e) 1.04, 90% interval 0.88 to 1.23.
Homologues: Orthologues: rabbit BCAS4 (83% identical), chimpanzee BCAS4 (80% identical), pig BCAS4 (79% identical), tropical clawed frog bcas4 (45% identical), Drosophila melanogaster Blos4 (21% identical). Paralogues in human: BLOC1S4 (38% identical).
Diseases named in the same sentence as BCAS4 in open-access papers:
BCAS4 is named in the same sentence as 13 diseases in open-access papers, as found by Europe PMC text mining. Sharing a sentence is not in itself a finding about the gene and the disease. The quoted sentences say what the papers report.
breast carcinoma (13 papers, 2013 to 2023). "Interestingly, several other HDAC1/7-SE upregulated targets, such as SNPH, CCANG4, PREX1, IGFBP5, IL34 and BCAS4 also demonstrate remarkable level of breast cancer associated over-expression, providing additional support for the relevance of the ET-125 signature." (PMID 36038558, 2022). "BCAS4 is either amplified, overexpressed or fused with the last two exons of BCAS3 to BCAS4 in breast cancer." (PMID 37019990, 2023). "Forced expression of in-frame fusion genes (SLC2A1–FAF1 and BCAS4–AURKA) resulted in increased viability of breast cancer cells." (PMID 24395524, 2014). "For example, the fusion BCAS3-BCAS4 (breast carcinoma amplified sequence 3/4), whose partner gene BCAS3 and BCAS4 were both widely known as overexpression sequence and fusion in breast cancer, detected in MCF-7 cell line was nominated as top one fusion driver by RWCFusion." (PMID 27506935, 2016). "BCAS3-BCAS4 gene fusion, which has previously been reported in breast carcinomas, was validated as the product of a fusion gene between BCAS4 and BCAS3, which resulted from amplification followed by a translocation event between the two loci chr20q13 and chr17q2372." (PMID 26113264, 2015). "Second, although cell lines constitutively harbouring the in-frame fusion genes identified in primary MPCs were not available, our results demonstrate that forced expression of SLC2A1–FAF1 and BCAS4–AURKA results in increased growth/survival in multiple breast cancer cells." (PMID 24395524, 2014). "Additionally, BCAS4 was found overexpressed in nine out of 13 different breast cancer cell lines." (PMID 24019942, 2013). "The facts that fusion reads spanned the fusion boundary between the BCAS4 and BCAS3 genes on chromosomes 20 and 17 proved that BCAS4 and BCAS3 gene fused and expressed in the MCF7 breast cancer cell line." (PMID 28761119, 2017). "BCAS4 and BCAS3 are located at 20q13 and 17q23, respectively, regions which undergo amplification, overexpression and fusion in breast cancers." (PMID 26040699, 2015). "In their study, western blotting showed that the expression of PER1 and PER2 decreased in the rhythm group, whereas the expression of breast carcinoma amplified sequence 4 (BCAS4), tubulin beta-2B chain (TUBB2B), and Roof Plate-Specific Spondin-4 (RSPO4) increased in the breast cancer group." (PMID 38074657, 2023). "Breast carcinoma amplified sequence 4 (BCAS4), a novel gene cloned from breast cancer cells, encodes a 211-amino acid cytoplasmic protein with no significant homologies to any known protein." (PMID 33083145, 2020). "Finally, only 1 (BCAS4/BCAS3), 1 (BSG/NFIX), 2 (STX16/RAE1, RAB22A/MYO9B) and 0 fusions have been reported by all the tools within the considered breast cancer cell lines." (PMID 28114882, 2017).
breast tumors (4 papers, 2010 to 2023). "For example, BCAS4 is an important gene for breast tumor development and progression." (PMID 26284108, 2015). "PTK6 maps to a chromosomal region (20q13.3) that is frequently amplified in breast tumors and amplicons spanning this region variably contain other suspected oncogenes, such as TDE1, NCoA3, BCAS4, and ZNF217." (PMID 20668531, 2010). "Even though the fold change of BCAS4 was less than the other three up-regulated proteins (periostin, ATAD2, and Ki-67), it was still attractive because BCAS4 was significantly increased in breast tumors compared to normal tumors reported by UALCAN." (PMID 37922300, 2023).
colon cancer (1 paper, 2013). "One of the translocation partners of BCAS3 is BCAS4, and fusion transcripts have been detected in MCF7 and HCT116 colon cancer cells." (PMID 24019942, 2013).
endometrial cancer (1 paper, 2023). Primary or metastatic malignant neoplasm involving the endometrium (mucous membrane that lines the endometrial cavity). "Overexpression of BCAS4 was also detected in endometrial cancer." (PMID 37019990, 2023).
intervertebral disc degeneration (1 paper, 2022). "A recent piece of research employing machine learning approaches and various microarray datasets revealed that BCAS4 might be a ceRNA regulator for the development of intervertebral disc degeneration." (PMID 35264942, 2022).
leukemia (1 paper, 2025). A malignant (clonal) hematologic disorder, involving hematopoietic stem cells and characterized by the presence of primitive or atypical myeloid or lymphoid cells in the bone marrow and the blood. "Regarding B cells, ATLL IgG strongly recognized proteins like SP110 and SP100, which are linked to B cell survival, NCOA3, associated with leukemia development, and BCAS4, related to cancer progression." (PMID 41303346, 2025).
metastasis (1 paper, 2014). The spread or migration of cancer cells from one part of the body (where they first appeared) to another. "Two of the in-frame expressed fusion genes identified in this study, SLC2A1–FAF1 and BCAS4–AURKA, were present both in the primary tumour MPC10 and in the corresponding synchronous lymph-node metastasis (MPC10LND)." (PMID 24395524, 2014). "Of interest, however, both SLC2A1–FAF1 and BCAS4–AURKA fusion genes were found to be present in the lymph-node metastasis of the index case MPC10." (PMID 24395524, 2014).
neuroblastoma (1 paper, 2022). Neuroblastoma (NB) is the most common solid, extracranial childhood tumor. "As previously stated, recent research using human neuroblastoma cell lines found that hsa-miR-185-5p regulates BCAS4 and SHISA7 in a ceRNA manner, which is consistent with our findings." (PMID 35264942, 2022). "In line with our results, a prior study on a human neuroblastoma cell line found that ceRNA regulation between BCAS4 and SHISA7 by hsa-miR-185-5p is conserved in humans." (PMID 35264942, 2022).
cancer (4 papers, 2009 to 2025). A tumor composed of atypical neoplastic, often pleomorphic cells that invade other tissues. "Of these PARD6B, BCAS4, and KCNG1 are expressed greater than two-fold higher in cancer samples with the amplification relative to normal." (PMID 19419571, 2009).
tumor (2 papers, 2014 to 2016). "Given that SLC2A1–FAF1 and BCAS4–AURKA fusion genes were present in both the primary tumour and lymph node metastasis of MPC10, we hypothesized that, albeit restricted to a single case, these fusion genes could constitute driver events." (PMID 24395524, 2014). "Of the eight validated fusions, two were predicted to be in-frame (SLC2A1–FAF1 and BCAS4–AURKA) and were both present in a single tumour (ie MPC10)." (PMID 24395524, 2014).
BCAS4 also shares sentences with these, for which no sentence is quoted: adenoma (1 paper); Alzheimer disease (1); pancreatic cancer (1).